PXDC1 (PX domain containing 1)
Synonyms: C6orf145
Tractability: Antibody: the Human Protein Atlas places it where antibodies can reach. PROTAC: ubiquitination databases record sites on it; its protein half-life has been measured.
Gene: Protein-coding gene on chromosome 6 (3,722,614 to 3,751,713, reverse strand). Ensembl gene ENSG00000168994.
Subcellular location (Human Protein Atlas): Plasma membrane
Gene Ontology:
Molecular function: phosphatidylinositol binding
Genetic constraint (gnomAD): Loss-of-function variants: 5 observed, 13.25 expected, observed/expected ratio (o/e) 0.38, 90% interval 0.2 to 0.79. The synonymous counts are far from expectation, so gnomAD's model fits this gene poorly and the ratio says little. Missense variants: 286 observed, 230.07 expected, observed/expected ratio (o/e) 1.24, 90% interval 1.13 to 1.37. Synonymous variants: 133 observed, 92.74 expected, observed/expected ratio (o/e) 1.43, 90% interval 1.25 to 1.66.
Homologues: Orthologues: chimpanzee PXDC1 (99% identical), rat Pxdc1 (93% identical), mouse Pxdc1 (92% identical), dog PXDC1 (82% identical), tropical clawed frog pxdc1 (81% identical), pig PXDC1 (78% identical), rabbit PXDC1 (73% identical), macaque PXDC1 (71% identical), zebrafish pxdc1b (71% identical), guinea pig PXDC1 (64% identical), zebrafish pxdc1a (39% identical).
Diseases named in the same sentence as PXDC1 in open-access papers:
PXDC1 is named in the same sentence as 3 diseases in open-access papers, as found by Europe PMC text mining. Sharing a sentence is not in itself a finding about the gene and the disease. The quoted sentences say what the papers report.
tumor (2 papers, 2021 to 2023). "In contrast, the highly expressed PXDC1 lacks a known function or any such PTMs yet is an established tumor marker in endothelial cells." (PMID 34368138, 2021).
PXDC1 also shares sentences with these, for which no sentence is quoted: acute myeloid leukaemia (1 paper); leukaemia (1).